CEACAM1 (CEA cell adhesion molecule 1)
Diseases named in the same sentence as CEACAM1 in open-access papers (continued):
Sharing a sentence is not in itself a finding about the gene and the disease.
tumor (continued). "To explore the possible effects of CEACAM1 in tumor cells to neutrophils, we detected the mRNA expression of IL-8, CXCL-6 and MCP-1 in different CEACAM1 transfection groups." (PMID 24587171, 2014). "The clinical relevance of these studies suggests that both CEACAM1 and CEACAM20 can be used to further assess the degree of tumor differentiation." (PMID 23358633, 2013). "We found that CEACAM1, CEACAM5 and CEACAM6 are present on tumor-derived MVs, and that human and murine endothelial cells release CEACAM1 expressing MVs." (PMID 24040308, 2013). "Insulin clearance by the liver has also been shown to be dependent on carcinoembryonic antigen-related cell adhesion molecule 1 (CEACAM1), a tumor suppressor belonging to the immunoglobulin superfamily." (PMID 23469261, 2013). "In the present study, we provide new insights into the multiplicity and diversity of CEACAM1, CEACAM5 and CEACAM6 expression and their functions in tumor development and progression." (PMID 20090913, 2010). "Tumor-specific disturbances of alternative splicing were also found for GLI1 oncogene and CEACAM1 tumor suppressor." (PMID 21082031, 2010). "Carcinoembryonic antigen-related cell adhesion molecule 1 (CEACAM1), a cell adhesion molecule expressed in a variety of cell types is a putative tumor suppressor gene." (PMID 18507857, 2008). "Primary tumours and LMs of all animals inoculated with UISO-Mel6 cells showed intense CEACAM1 expression and only low expression of the other markers." (PMID 17262079, 2007). "Tumours and metastases were analysed for HPA binding and expression of CEACAM-1 and L1, all markers indicative of metastasis in clinical studies." (PMID 17262079, 2007). "Two million control or CEACAM1 shRNA-transduced JEKO-1 cells expressing firefly luciferase were intravenously injected into immunodeficient NOD/SCID/IL2R-Gamma null (NSG) mice, and tumor growth was monitored by whole-body bioluminescence imaging." (PMID 40436855, 2025). "Through interactions with its ligands, including galectin-9, carcinoembryonic antigen-related cell adhesion molecule 1 (CEACAM1), and phosphatidylserine, TIM-3 inhibits T-cell function, promotes immune tolerance, and ultimately facilitates tumor immune evasion." (PMID 40918452, 2025). "Additionally, SMI402, which effectively inhibits TIM-3 from binding to CEACAM-1, HMGB-1, and PtdSer, has demonstrated its capacity to suppress tumor growth by promoting the infiltration and activation of CD8+ T cells and NK cell at the tumor site." (PMID 40332725, 2025). "CEACAM1 and CD147 are known to exhibit context-dependent expression, influenced by tumor grade, differentiation, and inflammatory background, which may blur their discriminatory ability in mixed-stage cohorts." (PMID 41357584, 2025). "TIM-3 interacts with multiple ligands, such as Galectin-9, CEACAM1, phosphatidylserine (PtdSer), and HMGB1, promoting tumor immune tolerance and CD8+ T-cell exhaustion, thus facilitating tumor progression." (PMID 40552075, 2025). "Additionally, CEACAM1 and CPOX were highly upregulated in the tumor cluster compared to the stroma cluster." (PMID 38291365, 2024). "CEACAM1 is known to be expressed on activated NK cells where it serves an inhibitory function by abrogating natural-killer group 2, member D (NKG2D)-signaling in response to NKG2D ligands expressed by tumor cells." (PMID 38956268, 2024). "CEACAM1 was upregulated in cored tumor epithelial tissue but the tumor/AT difference was not seen in bulk tissue." (PMID 38291365, 2024). "Consequently, targeting both CEACAM1 and TIM-3 concurrently holds promise as a strategy to enhance anti-tumor immune responses in CRC, as evidenced by successful outcomes in CRC mouse models." (PMID 38646539, 2024). "This showed CEACAM1 was expressed at significantly increased levels on TFH, TEM, and Th2 cells in the treatment-resistant samples and on Treg cells in both treatment-naive and -resistant tumor samples relative to healthy donor (HD) controls." (PMID 38956268, 2024).
tumor (continued). "CEACAM1, CEP55 and MELK were involved in tumor, inflammation, necrosis, and proliferation." (PMID 37589542, 2023). "Since this was accompanied by reduced tumor growth in xenografted mice it argues for a pro-metastatic effect of CEACAM1 rather than an effect on the primary tumor." (PMID 38077351, 2023). "Strikingly, the mean fluorescent intensities of the CEACAM1 labelling in the Venus+ populations were indistinguishable between the tumours at the two locations." (PMID 36656749, 2023). "Importantly, in vivo studies revealed that co-blockade of CEACAM1 and TIM-3 leads to enhanced anti-tumor immune responses with improved elimination of colon cancer tumors." (PMID 37567938, 2023). "CEACAM-1 induces the downregulation of NKG2D expression in tumor cells, while silencing it in mouse tissues will induce increased ligand expression of NK cells in tumor tissues." (PMID 37055849, 2023). "Thus, elevated levels of soluble CEACAM1 as well as membrane-anchored or soluble CEACAM5 proteins can modify immune response, angiogenesis and properties of epithelial cells favoring tumor-appropriated environment." (PMID 37691945, 2023). "While 5 genes were downregulated in tumor tissues, including PLAT, ERBB2, CEACAM1, NOX4, and UCHL1." (PMID 37056778, 2023). "Moreover, on the stromal tumor side, Fn binding to the T lymphocyte inhibitory receptors TIGIT and CEACAM-1 (via Fap-2 and the trimeric autotransporter adhesin CbpF, respectively) suppresses antitumor immunity, thereby indirectly promoting malignant growth." (PMID 36139097, 2022). "In addition, Metadherin on cancer cell surface communicated with CEACAM1 on macrophages to secrete C–C motif chemokine ligand 3 (CCL3), which promotes various tumor types of metastasis." (PMID 36497444, 2022). "The three types of conjugates (i.e., QD800-RGD, QD820-anti-CEACAM1, and QD840-anti-EGFR) were simultaneously detected in vivo, especially showed great potential to be used for tumor targeting agents with specific delineation of tumor region." (PMID 34976580, 2022). "Binding of Tim-3 and CEACAM1 promotes temporal differences in Restimulation-induced cell death (RICD) sensitivity in the effector T cell response, which plays a key role in regulating anti-tumour immunity and antiviral responses." (PMID 36368952, 2022). "NK-92 cells were used as a model for non-ADCC and direct NK killing of tumor cells because they express high levels of CEACAM-1 and have the CD56+ CD16neg phenotype." (PMID 35804808, 2022). "Another anti-CEACAM1 mAb, PMG1124, showed good results in a mouse model of a human tumor." (PMID 34943606, 2021). "We found positive staining of tumor cells in IHC staining for VISTA in 2.1% (3/145), Galectin-9 in 36.6% (53/145), PD-L1 in 40.7% (59/145), CEACAM-1 in 57.2% (83/145), HVEM in 74.5% (108/145), PVR in 77.9% (113/145) and HLA-E in 84.8% (123/145) of patients 29–33." (PMID 34135436, 2021). "TIM-3 is expressed on activated T cells and its signaling on cytotoxic T cells leads to T cell exhaustion which is mediated by carcinoembryonic antigen-related cell adhesion molecule 1 (CEACAM1), another well-known molecule expressed on tumor tissues and/or tumor infiltrating lymphocytes (TILs)." (PMID 34368221, 2021). "Since F. nucleatum only activates human TIGIT and CEACAM1 and not their murine homologs, tumor acceleration in the mouse models used here cannot involve impaired T cell and NK cell killing-activity via the activation of these important checkpoints." (PMID 32591509, 2020). "It is relevant given that Fap2 is the bacterial outer membrane adhesin employed by F. nucleatum to bind itself to its target, in the tumor microenvironment it has been shown to impair antitumoral NK cell functions and induce lymphocytic apoptosis through TIGIT and CEACAM1 activation." (PMID 32983143, 2020). "In contrast, CEACAM1-negative tumor cells expressed more cell surface NKG2D ligands and exhibited greater sensitivity to NK cell mediated cytolysis." (PMID 30871206, 2019).
tumor (continued). "Indeed, CEACAM1 can down-regulate MICA/B and ULBP1 from the tumor cell surface thus influencing their immunogenicity." (PMID 30871206, 2019). "We divided cases into two groups in presence or absence of expression of CEACAM1 in the deepest part of the tumor." (PMID 31481751, 2019). "Regarding tumor growth, only CEACAM1-4L, but not short isoform, suppressed tumor growth of NUGC3 cells." (PMID 31481751, 2019). "In our analysis of these isoforms in OvCa tumor tissue samples, we found high mRNA levels for CEACAM1-4L and -4S, whereas CEACAM1-3L and 3S were only weakly or not detectable." (PMID 30050594, 2018). "The N-terminal domain of CEACAM1, essential for intercellular adhesion, was not necessary for this tumor inhibitory effect." (PMID 30050594, 2018). "Evaluation of the potential role of CEACAM1 in anti-tumor responses in syngeneic tumor models using the anti-CEACAM1 mAb CC1 did not reveal any anti-tumor benefits of the mAb, as a monotherapy or in combination with an anti-PD-1 mAb." (PMID 30349641, 2018). "In addition, treatment with anti-CEACAM1 Ab CC1 in combination with TIM-3 or PD-L1 blockade resulted in robust CT26 tumor growth inhibition and an increase in tumor infiltrating CD8+ T cells in the CT26 model." (PMID 30349641, 2018). "In some cases, there was a strong cytoplasmic staining in <20% of the tumor cells, whereas in other cases, a weak or no CEACAM1 expression within tumor cells was detectable." (PMID 30050594, 2018). "In contrast, CEACAM1 does not show any prognostic significance in tumours with nodal involvement in our Western blot cohort." (PMID 30050594, 2018). "Following a detailed statistical analysis, the authors concluded that the absence of CEACAM1 in normal lung tissue and its expression in tumor cells argue against a tumor suppressive role of CEACAM1 in NSCLC." (PMID 30406153, 2018). "The presence of CEACAM1 on the primary tumor did not correlate with the development of metastases or survival." (PMID 27642217, 2016). "CEACAM1 was also expressed in some TIM-3-negative T cells and tumour cells." (PMID 26883990, 2016). "We measured soluble CEACAM1 using ELISA and assessed its relationship with tumor characteristics as well as its potential as a novel non-invasive diagnostic and prognostic indicator of OS." (PMID 27074014, 2016). "Finally, many of the genes down-regulated by EZH2 GOF in this study that modulate ECM-adhesion/signaling display altered expression or have been ascribed roles in tumor biology (e.g. NRCAM, CEACAM1, SORCS1, ADAM23, MME)." (PMID 25671303, 2015). "No CEACAM1 expression was found in normal cells adjacent to the tumours or in the negative controls." (PMID 23885995, 2013). "CEACAM1 mRNA levels also showed a significant negative correlation with tumour invasive extension (P = 0.039), which is in accordance with the serum protein levels." (PMID 23885995, 2013). "With continued passage, however, cells eventually reacquired a tumorigenic phenotype without losing expression of CEACAM1-4L, suggesting a strong selection for cells with proteomes that were unable to support CEACAM1 mediated tumor suppression." (PMID 22235309, 2012). "In this study patients with adenocarcinomas expressing CEACAM1 had a significantly worse overall and disease-free survival in comparison with those who had a CEACAM1-negative tumor." (PMID 20090913, 2010). "Primary tumours and lung metastases expressed L1 (+), whereas CEACAM1 was not expressed in either PTs or LMs." (PMID 17262079, 2007). "Thus, a further requirement of therapeutic anti-CEACAM1 antibodies is that they can block this potentially negative effect on NK mediated tumor killing." (PMID 38346003, 2024). "Notably, bivariant, dual marker density plots also showed that a discrete collection of CEACAM1+PD1+ cells could be detected in all manually gated subsets of CD4+ T cells within the treatment-resistant PBMC and tumor samples." (PMID 38956268, 2024).
tumor (continued). "However, we found CEACAM1 upregulated in PDAC tumor tissues but not detected in PDAC sera in this particular cohort." (PMID 38029961, 2024). "However, some studies have found that tumor-infiltrating CD8+ T cells expressing low level of CEACAM1 have no or minimal antitumor effects." (PMID 36712923, 2023). "Interestingly, CEACAM1-Tim3 interactions notably enhance the negative immunoregulatory capacity of Tim-3 and promote tumour evasion of immunosurveillance and immune killing." (PMID 36928507, 2023). "The tumor tissue in these patients may not express high enough CEACAM1 to produce a significant level of secreted CEACAM1 in the serum." (PMID 34837908, 2021). "In our opinion, cytoplasmic CEACAM1 might not function as a tumor suppressor and be related to tumor invasion and progression." (PMID 34368221, 2021). "CEACAM1-4S overexpression had less invasion and more lumen formations, but not less tumor growth." (PMID 31481751, 2019). "Moreover, a lack of CEACAM1 in WAP-T tumor cells resulted in increased Wnt signaling, promoted cellular invasiveness, and strongly enhanced the rate of metastasis of mammary adenocarcinomas in vivo." (PMID 30349641, 2018). "Several tissues overexpress CEACAM1 in endothelial cells such as normal or pathological nontumoral highly proliferating tissues (normal and/or pregnant endometrium, granulation tissue) or tumor tissues (such as solid human tumors)." (PMID 27642217, 2016). "CEACAM1, CEACAM5 and CEACAM6 may be released from epithelial tumors in microvesicles, whereas tumor endothelia only contain CEACAM1 which has a receptor function for other CEACAMs, influences T cell behavior and regulates the tumor matrix and microvascularization." (PMID 25832000, 2015). "Splicing patterns of CEACAM1 did not depend on the differentiation grade of tumor sample." (PMID 21082031, 2010). "Also, the mRNA levels of CEACAM1 and CEACAM6 (known membrane markers of malignant epithelial cells in various adenocarcinoma, including colon cancer), as well as MKI67 (a proliferation marker), were significantly higher at tumor center and tumor invasive margin than adjacent normal in PanCK(+) AOIs." (PMID 37964075, 2023). "In previous studies, we showed that NEO-201 specifically recognizes a tumor-associated variant of CEACAM5 and CEACAM6, which is not expressed in normal tissues, and proved that NEO-201 binds to both mammalian-expressed recombinant human CEACAM5 and CEACAM6 but not to CEACAM1 or CEACAM8 by ELISA." (PMID 36291783, 2022). "Immunohistochemical staining of paraffin embedded tumor tissue demonstrated the stability of the CEACAM1 knockdown in the subcutaneous tumors: Little to no CEACAM1 protein could be shown in the MeWo CEACAM1 kd tumors whereas high CEACAM1 was detected in the MeWo Luc tumors." (PMID 30089785, 2018). "Overlay of the scaled expression of CEACAM1, PD1, and PD-L1 on the viSNE maps of the 5 types of clinical samples showed their expression among the PBMC and tumor, but not healthy donor, samples." (PMID 38956268, 2024). "Although the expression of the other four ligands (HMGB1, CEACAM-1, LSECtin, and FGL-1) did not considerably affect the frequency of tumor-infiltrating CD8+ T cells, the negative relationship was consistent for the four important ligands." (PMID 38390332, 2024). "In our in vivo syngeneic tumor models, CT26, MBT2 and A20, anti-CEACAM1 Ab CC1 administered as a single agent therapy or in combination with an anti-PD-1 mAb (muDX400), provided no tumor growth inhibition." (PMID 30349641, 2018). "The anti-mouse CEACAM1 Ab, CC1, has been used in a number of preclinical studies to evaluate CEACAM1 as a potential anti-tumor target, however we were not able to find any published studies describing the ligand blocking capacity of this antibody." (PMID 30349641, 2018).
tumor (continued). "Taken together, tumor infiltrating CD8+ T cells express low levels of CEACAM1 and CC1 Ab mediates no or minimal anti-tumor effects in vivo, as a monotherapy or in combination with anti-PD-1 treatment." (PMID 30349641, 2018). "Also the source of high serum soluble CEACAM1 was not clear; higher CEACAM1 was noted in OS tumor tissues, but whether higher serum CEACAM1 were totally attributable to CEACAM1 overexpression in that tumor tissue requires further exploration." (PMID 27074014, 2016). "Other TIM-3 ligands, carcinoembryonic antigen cell adhesion-related molecule 1 (CEACAM1) and phosphatidylserine synthase (PTDSS1, not shown), which are ubiquitously expressed by tumor cells, showed overall reduction likely due to oncolysis and remodeling of the tumor microenvironment." (PMID 35193929, 2022). "Our work is consistent with the idea that immune cells reacting to invading areas of a growing tumor generate IRF-1 in the tumor perhaps through release of IFN-γ, which eventually leads to AS to generate CEACAM1 L-isoform expression not only on T cells but in non-inflamed epithelial cells as well." (PMID 24650050, 2014). "Rat HCC tumor cells transfected with CEACAM1a-4L displayed a significant decrease in tumor formation, progression, and burden compared to rat HCC cells transfected with CEACAM1b-4S and the negative control group, suggesting that CEACAM1 splice-switching therapy may inhibit HCC." (PMID 36741860, 2023).